IL17A (interleukin 17A)
Diseases named in the same sentence as IL17A in open-access papers (continued):
Sharing a sentence is not in itself a finding about the gene and the disease.
Stroke (continued). "In contrast to the brain, stroke markedly increased expression of inflammatory-related factors, including IL-17a, TNFα, and TLR4, in the gut; however, IL-1β and MCP-1 levels were not increased as in the brain." (PMID 34327147, 2021). "They showed that IL-17A-blocking antibody injected 3 h after stroke induction decreased infarct size and improved neurologic outcome in tMCAo mouse model." (PMID 33429982, 2021). "The goal of this study was to analyze the role of the IL-10 signaling for the control of the detrimental IL-17A response in stroke." (PMID 34772416, 2021). "IL-17A shows two distinct peaks of expression in the ischemic hemisphere: the first peak observed within 3 days and the second on day 28 after a stroke." (PMID 34445248, 2021). "In post-mortem brain tissue of patients who died within 24 h of stroke, IL-17A-positive T cells were detected in the infarcted area, suggesting their involvement in ischemic cascade injury after stroke." (PMID 33429982, 2021). "After stroke, males displayed greater mortality, worse sensory-motor deficit, and higher serum levels of proinflammatory cytokines IL-17A, MCP-1, and IL-5 as compared to females." (PMID 33451354, 2021). "In other CNS injury models, including stroke and traumatic brain injury, IL-17A promoted neutrophil infiltration, blood–brain barrier disruption, and the cytotoxicity of CD8+ T cells." (PMID 34344859, 2021). "In previous studies we observed increased IL-17A levels in ischemic brains as early as 6 h post stroke." (PMID 34772416, 2021). "To estimate the potential function of PD-1 in the control of IL-17A in γδ T cells in stroke, we analyzed PD-1 levels in γδ T cells from ischemic hemispheres and cervical lymph nodes." (PMID 34772416, 2021). "Recently, it has been shown that recombinant mouse IL-17A significantly attenuates damage of cortical astrocytes after stroke induction in a dose-dependent manner by inhibition of apoptosis." (PMID 32582147, 2020). "Which subsets of γδ T cells are the main producer of IL-17A in the lung after stroke and its potential modulation by CD147 warrant further investigation." (PMID 31447768, 2019). "Data showed that αCD147 treatment significantly decreased the stroke-induced upregulation of IL-17A in the lung γδT-17 cells." (PMID 31447768, 2019). "Accumulating evidence suggest that IL-17A plays a particular role in the delayed phase of the post-stroke inflammatory response; the neutralization of IL-17A was proved to be a potential therapeutic measure for ischemic stroke." (PMID 31921197, 2019). "IL-17A, produced mainly by activated Th17 cells, can induce the secretion of a variety of stroke-related cytokines, such as IL-6, TNF-α, IL-1β, CXCL1 and CXCL8." (PMID 29262579, 2017). "In the ischemic hemisphere, NaB decreased IL-18 at 2 days post stroke and IL-1beta, IL-17a, and IL-18 at 5 days post stroke." (PMID 27905989, 2016). "Although the IL-17A levels observed at 28 days after stroke were lower than those observed at 7 days, the levels of this cytokine were still higher than those detected in the controls." (PMID 24991091, 2014). "The results showed that IL-17A expression was significantly enhanced in IS patients at 7 days after stroke compared with the controls." (PMID 24991091, 2014). "In summary, these data suggest an imbalance between IL-17A-producing cells and regulatory T cells in patients with stroke." (PMID 24991091, 2014). "γδT cell counts did not correlate with lesion volume on magnetic resonance diffusion-weighted imaging or with clinical severity in the stroke patients, but γδT cells showed elevated levels of IL-17A (p = 0.048)." (PMID 24840735, 2014). "To investigate the potential role for IL-17A in stroke, we analyzed the plasma IL-17A levels in IS patients at 7 and 28 days after stroke and compared with the controls using ELISA." (PMID 24991091, 2014).
Stroke (continued). "In γδT cells there were increased levels of IL-17A in the stroke patients relative to the controls (p = 0.048) with a similar trend in IL-17A/IFN-γ ratio (p = 0.1) and with no alterations in IFN-γ levels." (PMID 24840735, 2014). "From 0–2 days after stroke (hyperacute phase), IL-6 and IL-17A levels showed positive correlations with overall monocyte counts (r=0.556, p<0.001, and r=0.597, p=0.001, respectively; Spearman’s rank correlation coefficient, data not shown)." (PMID 23936327, 2013). "IL-17A and Th17 cells play critical roles in stroke pathogenesis." (PMID 40948793, 2025). "We examined the expression level of IL-17A by enzyme-linked immunosorbent assay (ELISA) and Western blot and confirmed that LIPUS reduced the IL-17A content of brain tissues in stroke mice." (PMID 40290135, 2025). "Furthermore, data from GEO databases (GSE58294 and GSE16561) indicated that IL-17A expression was elevated in the peripheral blood of stroke patients compared to healthy controls." (PMID 40948793, 2025). "In conclusion, LIPUS improves long-term functional recovery by ameliorating the inflammatory state after stroke and inhibiting IL-17A/Notch1 signaling to promote WM repair, which provides a promising novel therapeutic approach for stroke and other demyelinating diseases." (PMID 40290135, 2025). "IL-17A and its receptor IL-17RA are involved in post-stroke inflammation and disruption of the BBB." (PMID 40289984, 2025). "However, IL-17A is involved in multiple neuroinflammatory conditions, such as MS and stroke, which share common IL-17 pathways during inflammation; this raises questions about the specificity of IL-17 inhibition as a treatment approach for AD." (PMID 38891990, 2024). "In addition, depletion of Th17 cells by IL-17A knockout ameliorates neuroinflammation and improves stroke outcome in MCAO mice." (PMID 38914581, 2024). "This supports that PPPE patients have an increased risk of cardiovascular disease later in life and is reinforced by the elevated levels of IL17A and sCD40L in the circulation of PPPE patients, both of which have been linked to myocardial infarctions, stroke, and cardiovascular deaths." (PMID 38745664, 2024). "This makes Th17 and IL-17A a possible target for the treatment of stroke." (PMID 37884768, 2024). "It is reasonable to believe that IL-17A will be an important target for post-stroke angiogenesis." (PMID 37884768, 2024). "This may have benefit, as there is evidence that IL-17a promotes neural precursor cell survival, synapse formation, and recovery after stroke." (PMID 38110993, 2023). "It suggests interleukin-17A neutralization as a potential therapeutic target in stroke." (PMID 37056478, 2023). "Of note, alterations of the gut microbiota also affect stroke outcome via IL-17A+ γδ T cells." (PMID 37056478, 2023). "Previous research has shown that astrocytic IL-17A promotes angiogenesis in the ischemic penumbra during stroke recovery, moreover, it was also found that anti-IL-17A monoclonal antibody (mAb) treatment or IL-17A knock-out attenuates its promoting effects on angiogenesis." (PMID 36873773, 2023). "This study will provide a basic theoretical basis for designing a comprehensive rehabilitation environment for stroke patients, it will also open up new ideas for the study of the mechanism of IL-17A-mediated nerve repair in the chronic phase of stroke recovery." (PMID 36873773, 2023). "Conversely, acutely post stroke, IL-17a contributes to the inflammatory cascade." (PMID 38110993, 2023). "The enriched environment may promote post-stroke angiogenesis through astrocytic interleukin-17A (IL-17A)." (PMID 37484824, 2023). "A variety of researches have demonstrated that suppressing the infiltration of γδ T cells and reduction of IL-17a and IL-21 levels via either pharmacological or genetic tools could improve the outcome of stroke." (PMID 35432162, 2022).
Stroke (continued). "With regard to neutrophil infiltration, IL-17A-producing γδ T cells have also been shown to promote neutrophil recruitment into the ischemic hemisphere early after stroke; however, a possible regulation by IL-1 in the context of ischemic stroke has not been studied yet." (PMID 35384588, 2022). "IL-17A is a pro-inflammatory cytokine, which is a predicted target of miR-20a-3p and a therapeutic target for anti-inflammatory drugs to improve recovery post stroke." (PMID 34570349, 2022). "In line with our findings, previous studies showed that administration of anti-IL-17A or astragaloside IV, an IL-17 inhibitor, ameliorated chronic stress- and stroke-related anxiety, respectively, suggesting a common role of IL-17A in anxiety that occurs in various CNS diseases." (PMID 35875667, 2022). "IL-17A has been shown to be increased following stroke, especially in males." (PMID 36825211, 2022). "IL-17A and IFN-γ could synergistically promote macrophage anti-infection immunity against stroke-associated pneumonia and acute pneumonic plague." (PMID 36330425, 2022). "In this study, we tested whether the anti-inflammatory cytokine IL-10 controls the early IL-17A response in T cells following experimental stroke." (PMID 34772416, 2021). "Many studies have found that inflammatory mediators are elevated after stroke, including IL-17a." (PMID 34327147, 2021). "Determined by qPCR and Western-blot, the expression of IL-17A showed two distinct peaks of expression in the ischemic hemisphere in a tMCAO mouse model: the first occurring within 3 days and the second on day 28 after stroke." (PMID 34975872, 2021). "Besides, several experimental studies have already shown that the neutralization of IL-17A is protective in stroke." (PMID 34772416, 2021). "However, prior to a clinical application of IL-17A antibodies in stroke, long-term data on the effects of IL-17A neutralization in both sexes should be collected to adjust for potential negative effects." (PMID 34772416, 2021). "Mechanisms that limit the detrimental IL-17A response in stroke are not well understood." (PMID 34772416, 2021). "Following stroke, IL-17A is mainly produced by innate-like γδ T cells." (PMID 34772416, 2021). "Consistent with increased IL-17A levels, we detected a significant upregulation of Cxcl1 and Mmp3 transcripts in the whole brain mRNA and a significant increase in absolute numbers of neutrophils at day 3 post-stroke in Il10−/− mice, respectively." (PMID 34772416, 2021). "Although IL-10 and IL-17A have opposing effects on stroke outcome, it is largely unknown whether these two cytokines interact." (PMID 34772416, 2021). "However, in stroke, the initial IL-17A driven inflammatory response is short-lasting, indicating that the sterile inflammatory response is effectively controlled." (PMID 34772416, 2021). "More importantly, we found that the increased IL-17A-expressing γδ T cells, as well as the increased IL-17A protein levels in both lung tissue and plasma after stroke, were significantly reduced in the αCD147-treated group compared with the isotype-treated group." (PMID 31447768, 2019). "IL‐17A, secreted by immune cells, plays a vital role in the stroke pathophysiology." (PMID 31020769, 2019). "Furthermore, in a murine stroke model, the neutralization of IL-17A results in reduced neutrophil infiltration, decreased infarct size and improved neurologic outcome." (PMID 31803028, 2019). "An experimental stroke model demonstrated that γδ T cells are the primary source of IL-17A." (PMID 24991091, 2014). "Both IL-6 and IL-17A in serum reached a peak level during the acute phase (3-7 days) after stroke." (PMID 23936327, 2013). "Therefore, the IL-17A/IL-17RA pathway induces the formation of M1 microglia after stroke." (PMID 40289984, 2025). "Besides, IL-17A-positive lymphocytes were detected in the autoptic brain tissue of stroke patients." (PMID 37581321, 2024).
Stroke (continued). "Therefore, we have performed a pRCT on IL-17A neutralization in experimental stroke." (PMID 37056478, 2023). "CDC42 was negatively correlated with the National Institutes of Health Stroke Scale (NIHSS) score (p < 0.001), whereas, in patients with AIS (all p < 0.050), it was positively associated with Th2 cells and IL-4 but negatively correlated with Th17 cells and IL-17A." (PMID 35547377, 2022). "Furthermore, the worse stroke outcome was abolished in the IL-17A knockout mice." (PMID 35663549, 2022). "Thus, our study improves the understanding of the IL-17A-dependent postischemic inflammatory response and may pave the way towards new immunomodulatory therapies for stroke treatment." (PMID 34772416, 2021). "Moreover, 3–5 days after stroke, IL-17-producing cells and IL-17A–positive lymphocytes are present in the brain parenchyma, probably expression of a disparity between IL-17A-producing cells and regulatory T cells." (PMID 31803028, 2019). "Th17 cells, which reach their peak peripheral levels 3–5 days post-stroke, infiltrate the ischemic tissue through a disrupted BBB, where they release IL-17A." (PMID 41357230, 2025). "In conclusion, this randomized, controlled trial demonstrates that IL-17A and TNF-α play an inflammatory role in the acute and subacute stages of stroke and aggravate brain injury, while VEGF-A exerts a neuroprotective effect." (PMID 37287803, 2023). "Interleukin-17A (IL-17A) was observed to peak twice after middle cerebral artery occlusion (MCAO) in mice, a practice used to model stroke in animals." (PMID 36671691, 2023). "Wild-type mice and Il17a–/– mice were subjected to MCAO and ischemic brains were analyzed by flow cytometry 24 h after stroke." (PMID 35663549, 2022). "Brain cytokine analysis at 24 h indicated that stroke resulted in substantially higher mean levels of IL-4, IL-6, TNF-α, IFN-γ, IL-10, and IL-17A in both C57Bl/6 and FVB mice." (PMID 25477780, 2014). "In conclusion, our study highlights that the P2X7 receptor may modulate the secretion of IL-17A in CD4+T cells, thereby exacerbating acute and subacute inflammation following stroke." (PMID 40948793, 2025). "Furthermore, we analyzed the human stroke database GSE58294 and identified a positive correlation between the expression levels of P2X7 and IL-17A, as well as P2X7 and IL-21." (PMID 40948793, 2025). "However, in vitro analyses of human blood samples of healthy controls and stroke patients incubated with CLA showed a significantly decreased production of IFN-γ and TNF-α, and a visual decrease of IL-17A and IL-6." (PMID 39372701, 2024). "Our results revealed that post-stroke EE treatment promoted functional recovery in a pro-angiogenesis manner through astrocytic IL-17A, which might promote CD34 and VEGF expression during the recovery phase of stroke." (PMID 36873773, 2023). "Given that IL-17A-producing γδ T cells promote early detrimental neutrophil infiltration after stroke, modulating their CD73 expression may attenuate post-stroke inflammation." (PMID 36917241, 2023). "To further elucidate the role of IL-17A on EE-mediated angiogenesis, we next evaluated the expression levels of VEGF, a well-studied growth factor for neovascularization, in the penumbra 21 days after stroke." (PMID 36873773, 2023). "And synergistic with TNF-α, IL-17a could enhance astrocytes to secrete CXCL1, leading to enhanced neutrophil infiltration in a mouse model of stroke." (PMID 35432162, 2022). "This is necessary to exclude that the neutralization has negative long-term consequences on post-stroke regeneration by inhibiting the recently discovered beneficial IL-17A effects on memory and behavior." (PMID 34772416, 2021). "γδ T17 cells are not the only source of IL-17, astrocyte-derived IL-17 A facilitates survival and neuronal differentiation of neural precursor cells in the recovery phase of stroke." (PMID 33868300, 2021).
Stroke (continued). "Astrocytes are a major cellular source of IL-17A, which maintains and augments subventricular zone (SVZ) neuronal precursor cell survival, neuronal differentiation, synaptogenesis, and functional recovery after a stroke." (PMID 34445248, 2021). "With this in mind, a targeted antagonization of IL-17A seems promising, irrespective of individual IL-10 levels pre-stroke." (PMID 34772416, 2021). "In the peripheral compartment, PD did not significantly modulate myeloid trafficking compared to the levels observed in the stroke-only group, nor were plasma concentrations of IL-1β, IL-17A, and GM-CSF altered." (PMID 30794103, 2020). "In the present study, we found that the expression of IL-17A was increased at 24 h in the lung tissue after stroke, which was mainly derived from γδ T cells, but not from CD4+ Th17 cells." (PMID 31447768, 2019). "We also found lower levels of IL-17A by NaB in the ischemic hemisphere only at later acute phase of stroke (5 days), but not at early acute phase, while in peripheral tissues lower levels of IL17A were found both at 2 and 5 days." (PMID 27905989, 2016). "Despite the presence of IL-17A-positive lymphocytes in autoptic brain of stroke patients, IL-17 blood level does not seem to be a good predictor of stroke outcome as compared to other cytokines such as IL-6." (PMID 25972779, 2015). "In this study, the increase in IL-17A but not in INF-γ levels in the γδT cells of the stroke patients suggests activation of the IL-23 and IL-17 cytokine expression pathway." (PMID 24840735, 2014). "In the present study, we found that CD14 dimCD16high non-classical Mo had a positive correlation with serum IL-17A from 12–16 days after stroke, suggesting that CD16+ monocytes producing IL-17 have a role in the pathogenesis of brain ischemia after the acute phase." (PMID 23936327, 2013). "In addition, in patients’ postmortem stroke tissues, positive staining of cells expressing IL-17A was higher in the infarcted area than in non-ischemic tissues and remained at higher levels on days 2–5." (PMID 37884768, 2024). "However, IL-17A production was not completely abolished in Il23r−/− mice after stroke, which is now explained by our findings on additional IL-1 effects on IL-17A production of γδ T cells." (PMID 35384588, 2022). "Given that IL-17A producing γδ T cells play a crucial role in neutrophil infiltration following stroke and are known to express IL1-R1, we hypothesized that IL-1 also drives neutrophil infiltration into the ischemic hemisphere through the induction of IL-17A in γδ T cells." (PMID 35384588, 2022). "Very recently, an experimental study in a murine model of stroke demonstrated that γδ T cells, rather than CD4+ Th17 cells, serve as a principal source of IL-17A in the injured brain and lung following stroke." (PMID 38965622, 2024).